OPN1MW3 (opsin 1, medium wave sensitive 3)
Description:
G protein-coupled photoreceptor that selectively activates G(i) proteins in response to medium-wavelength (green) light, thereby decreasing intracellular cAMP levels. Activation occurs when the opsin-bound cis-retinal chromophore absorbs a photon and isomerizes to all-trans-retinal, inducing a conformational change in the opsin that triggers a G protein-mediated phototransduction cascade. Mediates visual perception of green light in cone photoreceptor cells.
Synonyms: GOP; GCP
Tractability: Small molecule: a structure with a bound ligand is known. Antibody: UniProt places it where antibodies can reach, with medium confidence; UniProt predicts a signal peptide or a membrane-spanning region; its Gene Ontology location is reachable by antibodies, with medium confidence.
Gene: Protein-coding gene on chromosome X (154,257,582 to 154,271,090, forward strand). Ensembl gene ENSG00000269433.
Subcellular location: Cell membrane; Photoreceptor outer segment membrane
Gene Ontology:
Molecular function: G protein-coupled photoreceptor activity; G protein-coupled receptor activity
Biological process: visual perception; absorption of visible light; cellular response to light stimulus; G protein-coupled receptor signaling pathway; phototransduction; transducin-mediated opsin signaling pathway
Cellular component: cone photoreceptor disc membrane; photoreceptor outer segment; plasma membrane; membrane
Homologues: Orthologues: chimpanzee OPN1LW (99% identical), macaque OPN1MW3 (98% identical), macaque OPN1LW (96% identical), dog OPN1LW (90% identical), rabbit OPN1MW (88% identical), rat Opn1mw (88% identical), guinea pig Opn1mw (81% identical), tropical clawed frog opn1lw (79% identical), mouse Opn1mw (79% identical), zebrafish opn1lw1 (76% identical), zebrafish opn1lw2 (76% identical). Paralogues in human: OPN1MW (100% identical), OPN1MW2 (100% identical), OPN1LW (96% identical), RHO (43% identical), OPN1SW (42% identical), OPN3 (26% identical), OPN4 (24% identical), RRH (23% identical), OPN5 (20% identical).